INS (insulin)
Diseases named in the same sentence as INS in open-access papers (continued):
Sharing a sentence is not in itself a finding about the gene and the disease.
Insulin resistance (continued). "Other researchers and we suggested that insulin resistance is closely linked to neurodegenerative diseases like PD, and impaired brain insulin signaling is a feature contributing to neuronal dysfunction in these disorders." (PMID 37033942, 2023). "Pathway enrichment analysis showed increased insulin signaling and insulin resistance signatures in the LPI-injected MBOAT7-deficient mice." (PMID 37127068, 2023). "Increasing evidence has shown that MAFLD is associated with a variety of insulin-dependent metabolic damage, and patients with type 2 diabetes have significantly higher insulin resistance index." (PMID 37867509, 2023). "gingivalis causes a systemic inflammatory response, disrupts insulin signaling pathways, induces pancreatic β-cell hypofunction and reduced numbers, and causes decreased insulin sensitivity leading to insulin resistance (IR)." (PMID 37520442, 2023). "Dietary habits that continually expose tissues and cells to sustained post-meal hyperglycemia can impair first-phase insulin secretion and insulin action in insulin-sensitive tissues, increasing the risk for the development of insulin resistance and T2DM." (PMID 37242267, 2023). "Previous studies have revealed that ENPP1 directly interacts with IR and inhibits insulin signaling, and the binding of Gal-3 to IR causes insulin resistance." (PMID 37067034, 2023). "Thyroid dysfunction is associated with abnormal glucose-insulin homeostasis, and the triglyceride-glucose (TyG) index has been recommended as a convenient surrogate of insulin resistance (IR)." (PMID 37946276, 2023). "They consider the possibility of hypersecretion of insulin as a major cause of changes in both obese and lean cases, with the most likely factor being adiponectin down-regulation, potentially resulting in insulin resistance." (PMID 37881324, 2023). "The link between CRP and the acute-phase response, its contribution to impaired insulin signaling pathway, and in part, its links with obesity-driven systemic inflammation can explain the association with insulin resistance." (PMID 37891561, 2023). "Insulin resistance is associated with many pathological conditions, and an in-depth understanding of the mechanisms involved is necessary to improve insulin sensitivity." (PMID 37884540, 2023). "In adipose tissue, KLF14 gene expression has been associated with combined insulin resistance characterized by elevated levels of TGs and fasting insulin and decreased level of HDL-C." (PMID 36837818, 2023). "Conversely, diets negatively associated with T2DM promotes insulin secretion and improves insulin resistance by increasing SCFA-producing bacteria and decreasing H2S- and LPS-producing bacteria." (PMID 38260058, 2023). "It is common among individuals living with obesity or overweight for insulin levels to be elevated, and this is also associated with insulin resistance." (PMID 37763090, 2023). "Numerous studies have shown that defects in autophagy are an underlying factor in the development of insulin resistance in insulin-target tissues." (PMID 37065747, 2023). "Type 2 diabetes is predominantly characterized by insulin resistance, its progression is associated with insulin deficiency requiring insulin administration." (PMID 36804863, 2023). "PTEN haploinsufficiency and PTEN deletion ameliorate insulin sensitivity and defend against systemic insulin resistance associated with obesity." (PMID 37664840, 2023). "Genetic predisposition and epigenetic modifications can impact skeletal muscle metabolism and insulin sensitivity as well, which can contribute to susceptibility to insulin resistance." (PMID 38137918, 2023). "It has been reported to serve a purpose in the mediation of insulin action, and low concentrations have been linked to increased insulin resistance." (PMID 37125033, 2023). "These outcomes were in accordance with previous reports that IL-1β can regulate insulin secretion and is associated with insulin resistance." (PMID 37703108, 2023).
Insulin resistance (continued). "A complex pathogenesis involving pancreatic exocrine insufficiency, dysfunction of insulin secretion, and insulin resistance is likely the cause of T3cDM after AP." (PMID 36979645, 2023). "Impaired insulin-stimulated GLUT4 translocation in these tissues underlies insulin resistance, which is a major risk factor for type 2 diabetes and other metabolic diseases." (PMID 37248992, 2023). "Type II diabetes mellitus (T2DM) is a disease characterized by the progressive increase in cellular insulin resistance, leading to a state of persistent hyperglycemia causing a chronic increase of insulin production." (PMID 36906603, 2023). "These inflammatory markers also cause the downregulation of insulin activity, which leads to insulin resistance, endothelial dysfunction, and the development of MetS." (PMID 36939969, 2023). "There is evidence that insulin resistance is associated with insulin signaling deficiencies and that miR is involved in this process." (PMID 37786444, 2023). "Insulin resistance is characterized by a decline in the cellular response to insulin stimulation in the peripheral tissues and one of the causes is abnormal endogenous ROS production due to excessive fat intake." (PMID 36678333, 2023). "The results revealed that the enrichment of DEPs in the pathways were associated with insulin resistance (4%), insulin signaling pathway (4%), and AMPK signaling pathway (3%)." (PMID 37033250, 2023). "Because insulin resistance is caused by insulin signaling disorders, it is necessary to improve the insulin signaling pathway." (PMID 37432173, 2023). "Insulin resistance causes chronically high blood insulin levels, which is a growth-promoting hormone and hence a scientifically reasonable risk factor for PCa." (PMID 36928374, 2023). "The TyG index is associated with insulin resistance and dyslipidemia and has been recommended as a good indicator of the presence of cardiometabolic risk factors, particularly insulin sensitivity." (PMID 36765298, 2023). "TyG index was positively associated with fasting glucose, HbA1c, fasting insulin and the homeostatic model assessment of insulin resistance (HOMA-IR) index (all p < 0.001)." (PMID 36895032, 2023). "Underlying GDM is decreased insulin secretion by pancreatic beta cells and tissue insulin resistance." (PMID 38068941, 2023). "The development of T2DM is considered to be caused by insulin resistance, which is triggered by a combination of two main factors: defective insulin secretion by pancreatic β-cells and the inability of insulin-sensitive tissues to respond to insulin." (PMID 37175725, 2023). "The study also found that key metabolic risk factors such as insulin resistance, fasting insulin, and blood pressure improved similarly in all three groups." (PMID 37512005, 2023). "BCAA improves cirrhosis associated insulin resistance by inhibiting insulin mediated anti-apoptosis pathway in liver cancer cells." (PMID 37098004, 2023). "Elevated and uncontrolled blood glucose levels for a prolonged period due to insulin resistance and impaired insulin production caused by COVID-19 are commonly found." (PMID 37765098, 2023). "Obesity has long been associated with insulin resistance, an ominous condition characterized by the relative insensitivity of a target cell or a whole organ to insulin." (PMID 37965235, 2023). "While most of the identified variants affect insulin secretion, there are also variants that contribute to insulin resistance." (PMID 36409629, 2023). "This study also reported that LDFT in early pregnancy was associated with higher fasting insulin and insulin resistance at 24 weeks postpartum." (PMID 37057069, 2023). "In their view, development of insulin resistance in muscles and fat cells is caused by of an overexposure of the (post-hepatic) peripheral tissues to endogenous insulin." (PMID 36901984, 2023).
Insulin resistance (continued). "In general, qualitative changes in fat cells and the attenuation of insulin action due to inflammation are the main causes of insulin resistance." (PMID 36649006, 2023). "Insulin resistance, which is the impaired ability of cells to respond to insulin, is a common feature of obesity and is a risk factor for T2D." (PMID 37600709, 2023). "The rise in ANGPTL8 production was attributed to losing albumin, which causes insulin resistance and increased need for insulin in people with T2D and albuminuria." (PMID 37762544, 2023). "T2DM has been associated with insulin resistance, a compensatory state due to a continuous increase in insulin production." (PMID 37092526, 2023). "There were methylation abnormalities in genes related to liver development in embryos after PGT, some of which are related to glucose homeostasis and insulin response, increasing the risk of liver-derived insulin resistance in the offspring." (PMID 37065763, 2023). "MAPK signaling pathway is involved in cell signal transduction that contributes to insulin signaling and glucose transporter 4 expression levels, which are associated with insulin resistance in T2DM." (PMID 36987415, 2023). "SNS-Ubc9−/− and Ubc9fl/fl mice showed similar glucose intolerance caused by insulin resistance and insufficient insulin secretion at 16 and 29 weeks post-HFD, showing that the development of type 2 diabetes was comparable in both genotypes." (PMID 37947589, 2023). "There is a well-known link between weight and insulin sensitivity as weight loss improved insulin resistance, and weight is negatively correlated with M-value in IGT individuals." (PMID 37258943, 2023). "Our data revealed that metabolic parameters related to insulin levels and insulin resistance significantly associate with two distinct N-glycan structures—FA2B and A2G2S2." (PMID 37079606, 2023). "First, T2D is often associated with insulin resistance, unstable insulin concentrations, reduced ability of the liver to inhibit inappropriate hepatic glycogen release, and reduced ability of β-cells to overcome insulin resistance." (PMID 36672448, 2023). "Increase in circulating glucose and insulin levels associated with insulin resistance have been reported to stimulate de novo lipogenesis through the transcriptional regulation of ChREBP and SREBP-1, respectively." (PMID 37744933, 2023). "Excessive salt consumption has been demonstrated to cause insulin resistance in some earlier research by decreasing insulin sensitivity, preventing insulin mRNA expression, weakening insulin signaling, and raising angiotensin II production." (PMID 37727604, 2023). "Other studies have shown that serum Ca2+ dyshomeostasis is associated with the development of insulin resistance, reduced insulin sensitivity, and impaired glucose tolerance, all hallmarks of T2DM." (PMID 37999364, 2023). "The G972R IRS1 polymorphism has been linked to a 50% reduction in insulin sensitivity, suggesting that the GG genotype would reduce insulin resistance and the risk of CRC." (PMID 37284192, 2023). "It seems that high levels of fatty acids reduce cell sensitivity to insulin and eventually cause insulin resistance and hyperinsulinemia, which increases apelin secretion from adipose tissue." (PMID 37424869, 2023). "This increase was negatively associated with insulin sensitivity and positively related to the homeostasis model insulin resistance index." (PMID 37929036, 2023). "Inflammatory cytokines such as TNF-γ and IL-6 as well as the chemokine CCL2, produced by proinflammatory M1-like AT macrophages and hypertrophic adipocytes inhibit local insulin signalling pathways to cause adipose and systemic insulin resistance." (PMID 37642146, 2023). "Visceral adiposity is associated with increase in free fatty acid levels that cause insulin resistance by reducing insulin signalling at the target tissues." (PMID 37545918, 2023).
Insulin resistance (continued). "The underlying mechanism of insulin resistance is still uncertain, but skeletal muscle and adipose tissue have been shown to display insulin signaling defects." (PMID 37525285, 2023). "Type 2 diabetes (T2D) is a chronic metabolic disorder characterized by insulin resistance and progressive dysfunction and loss of insulin-producing pancreatic beta cells, resulting in insulin deficiency and elevated blood glucose." (PMID 37813862, 2023). "Its levels are inversely associated with fasting glucose and insulin levels, body fat, and insulin resistance in adults." (PMID 38203346, 2023). "Insulin resistance is a hallmark of type 2 diabetes, and the core of the model describes in detail the intracellular insulin resistance of adipocytes." (PMID 37286693, 2023). "Of further relevance to our finding, Cdc42 is implicated in insulin secretion and is linked to insulin resistance and diabetic nephropathy." (PMID 37365285, 2023). "Drugs commonly used clinically for treating type 2 diabetes can also reduce PAI-1, a phenomenon primarily associated with lower insulin precursors and improved insulin resistance, expanding the evidence for the clinical use of these drugs." (PMID 37020596, 2023). "MiR-29a was shown to be involved in glucose and fatty acid metabolism, whereas miR-222 has been related to insulin resistance and miR-132 has been associated with insulin secretion and glucose homeostasis." (PMID 36631877, 2023). "Lower levels of SHBG are mostly mediated by elevated levels of circulating insulin linked to the insulin resistance of obesity." (PMID 38203349, 2023). "Differential expression of miRNAs in HC and HS_MS1 groups associated with insulin signaling pathway and insulin resistance of common carp (n = 6)." (PMID 37091861, 2023). "A further investigation of intermediate traits for type 2 diabetes suggested that genetically predicted higher fitness was also significantly associated with lower fasting insulin, a marker of insulin resistance." (PMID 37400433, 2023). "Insulin induces endothelial NO synthase (eNOS) in ECs and determines the production of NO; insulin resistance, consequently, causes ECs dysfunction." (PMID 36689070, 2023). "Since in healthy people 75–80% of glucose is utilized by skeletal muscle, it is more likely that the main cause of insulin resistance is impaired insulin-stimulated glucose utilization by skeletal muscle." (PMID 36860209, 2023). "Western diets, which contain food with a high glycemic index, have a significant impact in terms of disturbances in glucose and insulin serum levels and are associated with the development of insulin resistance (IR)." (PMID 37626790, 2023). "Ectopic fat has been linked to the development of insulin resistance, reduced insulin clearance, metabolic syndrome, and NAFLD, which can progress to cirrhosis." (PMID 37123795, 2023). "Ceramides are bioactive molecules that play an important role in many cellular functions and have been associated with insulin resistance, altered insulin signaling, as well as inflammatory and apoptotic processes." (PMID 37628898, 2023). "Type one DM (T1D) and type two DM (T2D) are the most common and are caused by pancreatic β-cells insulin-production failure and acquired insulin resistance, respectively." (PMID 37065506, 2023). "In other words, insulin therapy in these patients is correlated with increased insulin resistance and an underlying proinflammatory state." (PMID 36984506, 2023). "Insulin resistance resulted in significantly higher fasting plasma glucose and insulin levels in the carriers of the risk genotypes." (PMID 37816730, 2023). "In order to clarify the possible mechanisms underlying the development of insulin resistance induced by high-fat diet treatment, we determined the relevant molecule expression on the insulin signaling pathway using Western blotting analysis." (PMID 37114144, 2023).
Insulin resistance (continued). "Insulin resistance is characterized by a persistent loss of insulin sensitivity and is a prevalent risk factor contributing to obesity, hypertension, cardiovascular diseases, and type 2 diabetes." (PMID 38053837, 2023). "Accumulation of toxic lipid intermediates is associated with myocardial insulin-resistance in heart failure, and active unloading leads to improved cardiac insulin signaling." (PMID 36845050, 2023). "Diabetic insulin resistance is caused by post-binding defects, and impaired beta-cell function advances these issues by altering insulin secretion." (PMID 37049602, 2023). "Type 2 diabetes mellitus (T2DM) is a complex chronic metabolic disorder resulting from a deficiency of insulin secretion and insulin resistance." (PMID 36845056, 2023). "Obesogenic diets are well known to cause insulin resistance in peripheral tissues, including fat, which rely on insulin to regulate glucose uptake." (PMID 37934726, 2023). "One of the main causes is insulin resistance, which is defined as the incapacity of the body cells to respond to normal or high levels of insulin." (PMID 37367903, 2023). "Insulin resistance, deficiency of insulin secretion, and reduction of its anabolic activity on target tissues alter the metabolism, and its reflected chronic metabolic disorder can lead to death." (PMID 37241737, 2023). "Defects in Akt phosphorylation, as seen in impaired insulin activation, are associated with development of muscle and adipose insulin resistance in obesity and T2DM." (PMID 36627919, 2023). "It was reported that therapy with oleanolic acid improved insulin sensitivity by increasing the expression of insulin receptor and glucose transporter proteins in HepG2 cells, which is significant because insulin resistance is a hallmark of type 2 DM." (PMID 36983154, 2023). "Insufficient insulin production and insulin resistance are the causes of T2DM, and these affect the control of the metabolism of proteins, lipids, and carbohydrates." (PMID 37107213, 2023). "Vit-D deficiency contributes to impaired insulin synthesis and insulin resistance, increasing the risk of prediabetes and T2D." (PMID 38201893, 2023). "It is proposed that these insulin defects are linked to increased adiposity and subsequent chronic inflammation, leading to the development of insulin resistance in tissues." (PMID 37297894, 2023). "As obvious, age is well-proven to be associated with progressive glucose intolerance, insulin resistance, and decreased insulin secretion." (PMID 37552330, 2023). "Marijuana use was linked to lower fasting insulin levels and a homeostasis model assessment of insulin resistance." (PMID 38011195, 2023). "The association between hyperinsulinemia and increased C-peptide level, which is a marker for long-term secretion of insulin and insulin resistance, with CRC risk was reported in many previous studies." (PMID 38082394, 2023). "T2DM is primarily caused by insulin resistance (IR), in which insulin cannot promote glucose uptake in skeletal muscle and adipose tissue and suppress hepatic glucose output." (PMID 36984867, 2023). "The most common forms of diabetes are type 1 diabetes caused by the absolute deficiency of insulin, and type 2 diabetes caused by insulin resistance." (PMID 36900567, 2023). "GPR21 expression is associated with developing type 2 diabetes (T2DM), a multifactorial metabolic disease caused by pancreatic β‐cell dysfunction, decreasing insulin production, insulin resistance, and obesity." (PMID 36721851, 2023). "SIRT1 is also necessary in insulin signaling, and its loss of function is linked with insulin resistance." (PMID 36768465, 2023). "Of note, obesity is frequently associated with reduced insulin sensitivity, resulting in the stimulation of insulin production by pancreatic beta-cells and the development of hyperinsulinemia and insulin resistance, which increase the risk of TC occurrence." (PMID 37763777, 2023).